CBX2 (chromobox 2)
Diseases named in the same sentence as CBX2 in open-access papers (continued):
Sharing a sentence is not in itself a finding about the gene and the disease.
leukemia (6 papers, 2014 to 2024). A malignant (clonal) hematologic disorder, involving hematopoietic stem cells and characterized by the presence of primitive or atypical myeloid or lymphoid cells in the bone marrow and the blood. "Here we provide the first evidence that the pan-HDACi SAHA induces CBX2 SUMOylation and degradation, the latter resulting in cell proliferation arrest and loss of self-renewal in leukemia cell lines." (PMID 29467492, 2018). "Our results identify CBX2 as a crucial player in leukemia progression and highlight a potential druggable CBX2-p38 MAPK network in AML." (PMID 35681235, 2022). "We previously reported that the histone deacetylase inhibitor SAHA controls CBX2 stability in leukemias, and we unraveled the specific molecular mechanism regulating CBX2 protein stability." (PMID 35681235, 2022). "Here we show that the HDAC inhibitor SAHA regulates CBX2 stability via a SUMO-triggered ubiquitin-mediated pathway in leukemia." (PMID 29467492, 2018). "For example, an extensive survey of 29 chromatin regulators in the K562 human leukemia cell line included data showing that endogenous CBX2 and CBX8 had remarkably coincident binding profiles." (PMID 24485159, 2014). "We found CBX2 overexpressed in leukemia both in vitro and ex vivo samples compared to CD34+ cells." (PMID 35681235, 2022). "It is interesting to speculate that reduced CBX2 levels may be required for the physiological differentiation of myeloid lineage cells and that targeting CBX2 in leukemia might lead to differentiation." (PMID 35681235, 2022). "Positive associations of CSNK1E in CLLE and CBX2 in LAML reached significance (ρ = 0.8750 and 0.8018, pFDR = 0.0306), consistent with their positive associations with many gene targets in these leukemia types." (PMID 33676569, 2021). "Finally, we show that CBX2-depleted leukemic cells display impaired proliferation, underscoring its critical role in regulating leukemia cell tumorogenicity." (PMID 29467492, 2018). "Additionally, CBX2-depleted leukemic cells display impaired proliferation, showing that CBX2 is required for leukemia cell clonogenicity." (PMID 29467492, 2018). "HDACi regulate CBX2 targets on chromatin, suggesting that they might indirectly modulate CBX2 in leukemia." (PMID 29467492, 2018). "In contrast, CBX2, CBX7, and CBX8 have oncogenic potential in hematopoiesis as they promote the survival of leukemia and lymphoma cells." (PMID 38426219, 2024). "We show that CBX2 is overexpressed in AML cells compared to CD34+ cells and to differentiated monocytes and macrophages, highlighting its possible function as a leukemia-driving oncogene." (PMID 35681235, 2022). "Taken together, our data identify a novel druggable CBX2-p38 MAPK network, highlighting its potential as a new therapeutic strategy in leukemia and, potentially, in other p38 MAPK-driven cancers." (PMID 35681235, 2022). "The present study identifies CBX2 as a critical factor required for the AML and provides new insights into its functional role in contributing to leukemia cell onset and maintenance." (PMID 35681235, 2022). "Further studies found the knockdown of CBX2 to facilitate the sumoylation activation of SUMO2/3, leading to the occurrence of leukemia." (PMID 34321009, 2021). "U937, K562, HL-60, and NB4 leukemia cells were transduced with lentiviruses expressing a non-targeting short hairpin RNA (shRNA) as control (shSCR) and two independent shRNAs targeting CBX2 gene (shCBX2) that display different knock-down efficacy." (PMID 35681235, 2022). "CBX2-depleted samples revealed the downregulation of gene sets mainly related to proliferation, such as E2F and MYC targets, inflammation, and oxidative phosphorylation, which is upregulated in several cancers including leukemia and lymphoma." (PMID 35681235, 2022). "Inhibiting CBX2 may therefore represent a possible strategy to target not only leukemia but also MAPK-driven tumorigenesis." (PMID 35681235, 2022).
osteosarcoma (6 papers, 2019 to 2024). A usually aggressive malignant bone-forming mesenchymal neoplasm, predominantly affecting adolescents and young adults. "In the present study, tissue microarray (TMA) analysis was performed to determine the association between CBX2 expression and clinical prognosis of osteosarcoma patients by immunohistochemistry." (PMID 31150156, 2019). "To explore the underlying mechanisms of CBX2 involved in osteosarcoma progression, we conducted bioinformatics analysis based on the sarcoma gene expression dataset from TCGA database." (PMID 31150156, 2019). "The CBX2/let‐7a axis provides novel insight into the mechanisms underlying osteosarcoma progression and may serve as a novel therapeutic target for osteosarcoma." (PMID 31150156, 2019). "To confirm whether let‐7a suppresses the osteosarcoma cells proliferation through targeting CBX2, we performed loss‐ and gain‐of‐function experiment in osteosarcoma cell lines." (PMID 31150156, 2019). "We further revealed the marked positive association between high CBX2 expression and the activation of DNA replication and cell cycle pathway in TCGA sarcoma cohort, indicating that CBX2 may play oncogenic role in osteosarcoma progression through regulating DNA replication and cell cycle." (PMID 31150156, 2019). "Consistently, result of colony formation experiment certified that unregulated let‐7a suppressed the proliferative activity of osteosarcoma cells, which was significantly reversed by overexpression of CBX2." (PMID 31150156, 2019). "Overexpression of let‐7a inhibits osteosarcoma cell proliferation, which was reversed by CBX2 overexpression." (PMID 31150156, 2019). "Further experiments revealed that CBX2 knockdown significantly impeded osteosarcoma cell proliferation and invasion ability in vitro, and suppressed the tumor growth in tumor xenografts model." (PMID 31150156, 2019). "Here we report that CBX2 is markedly upregulated in osteosarcoma and high CBX2 expression predicts poor clinical outcomes in osteosarcoma." (PMID 31150156, 2019). "Taken together, our study demonstrates that let‐7a/CBX2 plays a crucial role in osteosarcoma progression." (PMID 31150156, 2019). "Consistently, the rate of CBX2 staining was significantly increased in osteosarcoma tissues compared with normal tissues, while CBX2 immunoreactivity was observed primarily in the cell cytoplasm." (PMID 31150156, 2019). "More importantly, the inhibition effects of let‐7a on proliferation in osteosarcoma were reversed by the CBX2 overexpression." (PMID 31150156, 2019). "We then determined the clinical relevance of CBX2 in osteosarcoma, we found that CBX2 expression was progressively increased gradually during osteosarcoma progression in patients with metastasis or recurrence." (PMID 31150156, 2019). "Functional analysis showed that CBX2 silencing osteosarcoma cells exhibited a significantly suppressed proliferation and metastasis capacity." (PMID 31150156, 2019). "Overexpression of let‐7a inhibits osteosarcoma cell proliferation, while increasing CBX2 expression reverses this effect." (PMID 31150156, 2019). "To detect the biological function of CBX2 on osteosarcoma progression, we disrupted CBX2 expression in osteosarcoma cells and the results showed that the CBX2 silencing markedly inhibited the tumor proliferation in vitro and tumorigenesis in vivo." (PMID 31150156, 2019). "We found that CBX2 was a significant higher expression in osteosarcoma cells than normal osteoblast cells." (PMID 31150156, 2019). "Next, cell counting kit‐8 (CCK‐8) assays were conducted to assess the influence of CBX2 silencing on osteosarcoma cell proliferation." (PMID 31150156, 2019). "We found that CBX2 is dramatically upregulated in osteosarcoma tissues and high CBX2 expression was correlated with metastasis, recurrence, and chemotherapy response, as well as unfavorable prognosis in patients with osteosarcoma." (PMID 31150156, 2019).
osteosarcoma (continued). "Consistent with this notion, invasive ability of osteosarcoma cell was dramatically suppressed following CBX2 knockdown." (PMID 31150156, 2019). "Consistent with the survival analysis results in osteosarcoma, upregulated CBX2 expression was correlated with unfavorable prognosis in patients with sarcoma." (PMID 31150156, 2019). "CBX2 could serve as a promising prognostic biomarker and potential therapeutic target for osteosarcoma patients." (PMID 31150156, 2019). "In conclusion, we determined that CBX2 is upregulated in osteosarcoma and might serve as a prognostic factor for osteosarcoma." (PMID 31150156, 2019). "Moreover, Kaplan‐Meier analysis revealed that upregulated CBX2 expression was correlated with worse overall survival in patients with osteosarcoma." (PMID 31150156, 2019). "Knockdown of CBX2 decreased the proliferation and invasion of osteosarcoma cells." (PMID 31150156, 2019). "Taken together, these finding indicated that CBX2 might function as an oncogene in human osteosarcoma likely through regulating cell cycle and DNA replication, and CBX2 may serve as a putative therapeutic target in osteosarcoma." (PMID 31150156, 2019). "After validating CBX2 that acts as an oncogene, we confirmed that miRNA let‐7a could directly target CBX2 in osteosarcoma cell lines through bioinformatics prediction and experimental validation." (PMID 31150156, 2019). "Altogether, these findings indicated a close association between CBX2 overexpression and worse osteosarcoma prognosis, and suggest that CBX2 may function as an oncogene in the development of osteosarcoma." (PMID 31150156, 2019). "Previous studies have revealed that numerous miRNAs are dysregulated and contributed to the initiation and development of the osteosarcoma; we hypothesized that miRNA might be involved in the mechanism of CBX2 dysregulation in osteosarcoma." (PMID 31150156, 2019). "Taken together, our study demonstrates the importance of let‐7a/CBX2 axis in osteosarcoma progression and CBX2 might be exploited as a potential target for cancer therapy." (PMID 31150156, 2019). "Taking the functions of CBX2 and let‐7a contributed by our and others' endeavors into account, we reveal a novel mechanism for let‐7a as a tumor suppressor via targeting CBX2 in the progression of osteosarcoma." (PMID 31150156, 2019). "Meanwhile, downregulation of CBX2 suppressed the osteosarcoma tumor xenografts in nude mice." (PMID 31150156, 2019). "Moreover, we examined whether CBX2 knockdown could influence the invasion ability of osteosarcoma cells by Matrigel invasion assay." (PMID 31150156, 2019). "Furthermore, we found that CBX2 silencing could significantly decrease EdU incorporation rate in osteosarcoma cells via EdU incorporation assays." (PMID 31150156, 2019). "To determine the expression and potential functions of CBX2 in osteosarcoma, we first analyzed the CBX2 expression in normal osteoblast cells (HFOB and HOBC) and several osteosarcoma cell lines." (PMID 31150156, 2019). "Serving as an oncogene, CBX2 promoted cell proliferation and invasion in CRC and osteosarcoma." (PMID 36140750, 2022). "Linear correlation analysis showed that the expression of CBX2 was negative correlated with let‐7a expression in osteosarcoma tissues." (PMID 31150156, 2019). "We found that CBX4 and CBX8, but not CBX2 or CBX6, was overexpressed in all 16 osteosarcoma tissues compared with the 4 normal tissues." (PMID 32111827, 2020). "In addition, depletion of other CBX family members, such as CBX2 and CBX6, or PRC1 core subunits, Ring1a and Ring1b, did not consistently show to affect the mRNA level of Runx2 in these osteosarcoma cell lines." (PMID 32111827, 2020).
glioblastoma (5 papers, 2010 to 2025). The most malignant astrocytic tumor (WHO grade IV). "CBX2 has been shown to enhance the sphere-forming ability of glioblastoma by regulating the Phosphatidylinositol 3-Kinase/Akt Pathway signaling pathway." (PMID 39988672, 2025). "The expression levels of CBX6 and CBX7 are downregulated, and the expression of CBX8 is upregulated in glioblastoma samples, whereas the expression of CBX2 and CBX4 remain unchanged." (PMID 24260522, 2013). "We found that compared to differentiated glioblastoma cells (DGC), expression of CBX2, CBX3, and CBX5 were upregulated, while CBX1, CBX4, CBX6, CBX7, and CBX8 were downregulated." (PMID 39988672, 2025). "Surprisingly, some PRC1 components (BMI1, CBX2, CBX7) were downreglated in glioblastoma compared to normal brain." (PMID 20920292, 2010).
liver cancer (5 papers, 2018 to 2024). An epithelial or non-epithelial malignant neoplasm that arises from the liver. "CDCA6 (CBX2) was reported to be strongly associated with the Hippo pathway and yes-associated protein in liver cancer cells." (PMID 34082692, 2022). "Eventually, a four-gene (karyopherin subunit alpha 2(KPNA2), suppressor of cytokine signaling 2(SOCS2), GTP-binding protein 4(GTPBP4), and chromobox 2(CBX2)) signature model was constructed by multivariate analysis showing that they were independent prognostic factors for liver cancer." (PMID 35479398, 2022). "Moreover, higher mRNA expression of CBX2 was also significantly related with poorer OS of liver cancers patients and was an independent prognostic factor for shorter OS of liver cancer patients, indicating an oncogenic role of CBX2 in the HCC." (PMID 30481161, 2018).
breast tumors (4 papers, 2017 to 2025). "Our work attempts to address some of these issues, at least in part, by identifying that CBX2/7‐driven aerobic glycolysis is associated with breast tumor aggressiveness and poor prognosis." (PMID 33400401, 2021). "CBX2 overexpression in breast tumours was associated with the upregulation of genes involved in cell cycle progression and with poorer 5-year survival." (PMID 30820027, 2019). "Novel computational and experimental evidence suggest that chromobox 2 (CBX2), one of the OCs that we identified, is associated with poorer clinical outcomes and functions as a regulator of breast tumour cell growth." (PMID 30820027, 2019). "Noteworthily, CBX1 and CBX2 were associated with chemoresistance whereas CBX7 was associated with tamoxifen sensitivity, as well as chemosensitivity in breast tumors." (PMID 29190923, 2017). "Regardless, these results provide evidence of the relevance of CBX2/7 in predicting sensitivity to anticancer drugs and suggest that CBX2High breast tumors may be more likely to benefit from methotrexate and rapamycin treatment." (PMID 33400401, 2021). "Targeted inhibition of CBX2 may therefore pose a novel therapeutic strategy with minimal side effects on healthy tissue for women whose breast tumours overexpress CBX2." (PMID 30820027, 2019). "Moreover, CBX2/7 mRNA correlated significantly with protein levels in TCGA breast tumor samples." (PMID 33400401, 2021). "Furthermore, the distribution of CpG β-values for the single most influential covariate in the CBX2 model, a CpG site located within the second intron of the CBX2 gene, showed a clear reduction in DNA methylation (P-value < 1 × 10−8, Wilcoxon rank-sum test) in breast tumours that overexpress CBX2." (PMID 30820027, 2019). "CBX1 and CBX2 might be important predictor of chemoresistance in breast tumors." (PMID 29190923, 2017). "Reproducibly in both datasets, CBX2 was found to be the most upregulated and CBX7 as the most downregulated isoforms in breast tumors compared with normal tissues." (PMID 33400401, 2021). "Underpinning the biological significance of metabolic roles, CBX2 and CBX7 were found to be the most up‐ and downregulated isoforms, respectively, in breast tumors compared with normal tissues." (PMID 33400401, 2021). "Consistent with effect of CBX2/7 silencing on proliferation, CBX2/7 protein correlated significantly with proliferation markers CCNB1 and Ki67 in TCGA breast tumor tissues." (PMID 33400401, 2021). "Further, we evaluate the biological and clinical relevance of identified metabolic roles of CBX2 and CBX7 to show that these two isoforms are most differentially expressed in breast tumors and are informative about prognosis and drug sensitivity." (PMID 33400401, 2021). "CBX2 and CBX7 are over‐ and underexpressed in a subset of tumor samples; percentage of CBX2 over‐ and CBX7 underexpressing samples increased with breast tumor aggressiveness in both datasets." (PMID 33400401, 2021). "We conjectured that CBX2 and CBX7 may modulate growth signaling to induce metabolic reprogramming in breast tumors." (PMID 33400401, 2021). "Consistently, genomic data also showed higher amplification frequency of CBX2, not CBX7, in breast tumors." (PMID 33400401, 2021). "Moreover, CBX2 and CBX7 expression (not other isoforms) correlated strongly, but oppositely, with breast tumor subtype aggressiveness and the proliferation markers." (PMID 33400401, 2021).
metastatic tumors (4 papers, 2016 to 2024). "We next examined CBX2 expression in matched primary tumor, ascites-associated tumor cells, and metastatic tumors from five HGSOC patients (GSE73064)." (PMID 30478317, 2018). "Consistent with this notion, we have also shown that CBX2 expression is elevated in metastatic tumors compared to those remaining local to the prostate." (PMID 26877821, 2016). "In the LTL313B/H model, we observed a high expression of CBX2 solely in the metastatic tumor line LTL313H." (PMID 26877821, 2016). "Firstly, we performed the TF enrichment analysis between primary tumors and metastatic tumors, and finally, seven TFs were identified as differentially expressed TFs, including CBX2, CDX2, FOXA2, KLF4, NANOG, NCAPG, and TFAP2A, which was demonstrated in a heatmap and a volcano plot." (PMID 38702698, 2024). "To determine whether gene expression changes observed upon CBX2 silencing had clinical relevance, we analyzed the expression of CRGs in a large clinical dataset containing both primary and metastatic tumors." (PMID 26877821, 2016). "Additionally, we have also shown that CBX2 expression is dramatically elevated in metastatic tumors compared to metastatic absent patient." (PMID 31150156, 2019). "To ensure that overexpression of CBX2 in metastatic PCa tissues was not solely a property of the LTL313B/LTL313H xenograft model, we assessed the expression of CBX2 in primary and metastatic tumors from PCa patients using the Oncomine database." (PMID 26877821, 2016).
serous ovarian cancer (4 papers, 2018 to 2023). "In this study, IHC staining demonstrated that CBX2 expression was obviously elevated at the translational level in serous ovarian cancer tissues compared with normal ovarian tissues, which was similar to a previous finding." (PMID 32742466, 2020). "For example, CBX2 suppresses apoptosis in high-grade serous ovarian cancer (HGSOC) cells." (PMID 37662906, 2023). "Finally, the expression levels of CBX1 and CBX2 at the transcriptional level in serous ovarian cancer patients were related to poor OS and PFS, and CBX3 was associated with poor OS." (PMID 32742466, 2020). "Thus, the CBX1 and CBX2 mRNA levels in serous ovarian cancer patients were related to poor OS and PFS, and CBX3 mRNA was related to poor OS." (PMID 32742466, 2020). "In summary, our results showed that the CBX1, CBX2 and CBX3 proteins were overexpressed in serous ovarian carcinoma tissues compared with normal ovarian tissues." (PMID 32742466, 2020). "Furthermore, elevated expression of CBX2 mRNA was shown to be involved in both poor OS (HR = 1.47 (1.11 - 1.95), P = 0.0066) and PFS (HR = 1.51 (1.18 - 1.93), P = 0.0010) for serous ovarian cancer patients." (PMID 32742466, 2020).